CXCL1 (C-X-C motif chemokine ligand 1)
Diseases named in the same sentence as CXCL1 in open-access papers (continued):
Sharing a sentence is not in itself a finding about the gene and the disease.
migraine (4 papers, 2017 to 2022). "While IL-1β has a well-identified role in migraine pathogenesis, CXCL1 and CCL2 are associated with pain hypersensitivity and more recently with migraine." (PMID 36359895, 2022). "Consistent with the higher level of IL-6, which is a strong activator of CXCL1, we found high levels of CXCL1 in all but one (patient S) migraine patients." (PMID 28900389, 2017). "Therefore, a comparison between VM patients and migraine patients, namely IL- 1β, CCL3, CCL22, and CXCL1 levels, could be beneficial to understand if there is a shared cytokine profile between migraine and VM or if this cytokine signature is specific to VM." (PMID 31214186, 2019). "Levels of IL-1β, CCL3, CCL4, CXCL1, CCL22, and CCL8 were also measured in 55 healthy controls and 64 migraine patients." (PMID 34575163, 2021). "Cytokines CXCL1, HGF, and LIF appear to be also higher in at least one patient with migraine with aura." (PMID 28900389, 2017). "CXCL1, like IL-6 is a pro-inflammatory and pro-nociceptive cytokine that is co-expressed in sensory neurons together with neuropeptide CGRP, which is a major migraine mediator." (PMID 28900389, 2017). "Therefore, we measured the levels of IL-1β, CCL3, CCL4, CXCL1, CCL22, and CCL18 in a cohort of 83 patients with MD, which included 44 EOMD and 39 LOMD, and 64 patients with migraine without vestibular symptoms to control the effect of migraine itself on cytokine levels." (PMID 34575163, 2021).
myelofibrosis (4 papers, 2022 to 2024). A partial or complete replacement of the bone marrow stroma by fibrous tissue. "Here, we demonstrate that, in addition to high levels of TGF-β, the megakaryocytes from the bone marrow of the Gata1low mouse model of myelofibrosis express high levels of murine (m)CXCL1, the murine equivalent of hCXCL8, and its receptors CXCR1 and CXCR2." (PMID 35392239, 2022). "Given the great interest in TGF-β1, LCN2, and CXCL1 in the pathobiology of myelofibrosis, the serum levels of these three inflammatory cytokines were compared by ELISA using larger cohorts of mice." (PMID 35204735, 2022). "The relative frequency of iFibs was 2-fold higher in myelofibrosis mice than controls, and expression of chemokine genes was strongly enriched in the iFibs with significantly increased per cell expression of chemokines in MPL vs. control fibroblasts, including Kitl, Cxcl12, Ccl2, Cxcl1." (PMID 39383242, 2024).
neuroblastoma (4 papers, 2020 to 2023). Neuroblastoma (NB) is the most common solid, extracranial childhood tumor. "Studies have found that both subtypes of MDSCs along with monocytes and neutrophils are recruited by chemokines, including C-C Motif Chemokine Ligand 2 (CCL2), CCL7, and chemokine (C-X-C motif) ligand 1 (CXCL1), produced by tumor cells and TAMs in neuroblastoma and other tumors." (PMID 32983125, 2020). "Furthermore, CXCR5/CXCL13 and CXCR1/CXCL1 interactions may specifically contribute to neuroblastoma bone marrow metastasis in part by facilitating transmigration of neuroblastoma cells through the bone marrow endothelium." (PMID 34831167, 2021). "PS suppressed the levels of IL-6, IL-10, CXCL1, and CXCL2 induced by paclitaxel in a neuroblastoma cell line, and macrophage activation to the M1 proinflammatory phenotype." (PMID 38347876, 2023). "In co-cultured murine neuroblastoma and microphage cell lines (Neuro-2A and RAW264.7) that mirror the inflammatory infiltrate of CIPN, we evaluated the effect of PS on the expression of four cytokines, IL-6, IL10, CXCL-1, and CXCL-2, all involved in CIPN." (PMID 38347876, 2023).
periodontal disease (4 papers, 2022 to 2025). "CRCR4, CXCL1, and SAA1 regulate immune cell distribution and induce inflammatory cell recruitment in periodontal diseases." (PMID 36457739, 2022).
Sjögren syndrome (4 papers, 2021 to 2024). "CXCL1 has been found to increase in conjunctiva and tears in Sjögren syndrome dry eye, in tears of aged C57BL/6 mice and in the corneal epithelium of the CD25 knockout mouse Sjögren syndrome model." (PMID 38560382, 2024).
acute pancreatitis (3 papers, 2012 to 2023). An acute inflammatory process that leads to necrosis of the pancreatic parenchyma. "Increased CXCL1 levels have also been reported in acute pancreatitis-associated ALI/ARDS, which accounts for 50%–90% of all deaths from pancreatitis." (PMID 36164329, 2022). "Additionally, emodin ameliorates the lung injury associated with acute pancreatitis by inactivating the NLRP3/IL‐1/CXCL1 signaling." (PMID 36751097, 2023). "CXCL1, CXCL5, and CXCL8 levels in the plasma and BAL were observed to be elevated in patients at risk for or with ARDS, and a similar finding was made in the case of severe acute pancreatitis when they were found to be strong predictors of disease severity." (PMID 36164329, 2022).
adenomyosis (3 papers, 2022 to 2024). The growth of endometrial tissue inside the muscular wall of the uterine corpus. "A previous study demonstrated that downregulation of CXCL1 can lead to adenomyosis development due to its interaction with STAT339." (PMID 38745005, 2024). "Another study has found that tumor necrosis factor-α and vascular endothelial growth factor (VEGF) can stimulate the release of the C-X-C motif chemokine ligand 1 (CXCL1) in endometrial epithelial cells derived from the endometrium of patients with adenomyosis." (PMID 39456936, 2024). "Consequently, CXCL1 attracts migration of vascular endothelial cells, promoting local neovascularization and contributing to the progression of adenomyosis." (PMID 39456936, 2024).
alcoholic cirrhosis (3 papers, 2013 to 2015). "This analysis confirmed carriage of the CXCL1 rs4047 A allele as an independent risk factor for alcoholic cirrhosis (OR 1.485; 95%-CI: 1.084-2.035; p=0.014)." (PMID 24260493, 2013). "Our cross-sectional study revealed that the CXCL1 A allele is more frequent among patients with alcoholic cirrhosis compared to healthy controls and to patients with alcohol abuse in the absence of liver damage." (PMID 24260493, 2013). "The present investigation focused on the potential influence of the CXCL1 rs4074 single nucleotide polymorphism on the occurrence of alcoholic cirrhosis and HCC in a cohort of European descent." (PMID 24260493, 2013). "To check if carriage of the CXCL1 rs4047 A allele is an independent risk factor for alcoholic cirrhosis when other known risk factors such as age, gender, and the PNPLA3 rs738409 risk variant were also taken into account, we calculated a Cox regression model." (PMID 24260493, 2013). "The enhanced CXCL1 serum levels in carriers of the rs4074 A allele together with their increased frequency in patients with alcohol induced cirrhosis suggest the CXCL1 rs4074 A allele as a genetic risk factor for alcoholic cirrhosis." (PMID 24260493, 2013). "Multivariate analysis confirmed the CXCL1 rs4074 risk variant as independent risk factor for alcoholic liver cirrhosis in addition to age, gender and the PNPLA3 148M risk variant." (PMID 24260493, 2013). "Thus carriage of the CXCL1 rs4047 A allele was observed significantly more frequently among patients with alcoholic cirrhosis (65.3%) than in alcoholic controls (54.8%, OR=1.55; 95%CI=1.025-2.350; p=0.04) or healthy controls (53.8%, OR=1.62; 95%CI=1.212-2.151; p=0.001)." (PMID 24260493, 2013). "Distribution of the CXCL1 genotypes (GG/GA/AA) was 159/219/80 in patients with alcoholic cirrhosis, 52/44/19 in alcoholic controls and 158/140/44 in healthy controls." (PMID 24260493, 2013). "In contrast to sera from healthy controls, sera from patients with alcoholic cirrhosis induced CXCL1 secretion in TLR2- (p=0.016) and TLR4- (p=0.008) transfected HEK293 cells." (PMID 24260493, 2013). "To determine whether the CXCL1 rs4074 G/A polymorphism influences the CXCL1 expression in patients with high alcohol consumption (>300g per week), we measured CXCL1 serum levels in 66 samples of patients with alcoholic cirrhosis and healthy controls, respectively." (PMID 24260493, 2013).
alveolitis (3 papers, 2021 to 2024). "Nasal inoculation of cotton rats with a recently isolated EV-D68 strain (VANBT/1) significantly upregulated pulmonary cytokine mRNA levels (CCL2, CCL5, CXCL1, CXCL10, IL-6, IFN-β, and IFN-γ) and provided histological evidence of peribronchiolitis and alveolitis." (PMID 34887856, 2021). "Reflecting the significant reduction in expression of chemokines (CCL3, CCL4, CXCL1, CXCL2, and CXCL10) in the lung, the levels of alveolitis in PKD1mKO at 24 h after the S. rectivirgula exposure was also significantly reduced compared to the levels of alveolitis in WT." (PMID 39464896, 2024).
amyloid (3 papers, 2019 to 2024). "To assess whether the increased amyloid plaque burden resulted in an exacerbation of pro-inflammatory responses, we measured levels of the inflammation-associated molecules CXCL1, CCL3, IL-33, TNFα, IL-6, and IL-1β by multiplexed MSD ELISA." (PMID 32943069, 2020). "This was associated with a reduced CXCL1, IL-1β, TNF-α-level and microgliosis, which correlated with amyloid deposition and total Aβ." (PMID 30872722, 2019). "Moreover, amyloidomas from neutrophil depleted mice had enhanced expression of CXCL-1 a potent neutrophil chemokine indicating the potential need of this cell type in amyloid clearance." (PMID 39600710, 2024).
aneurysm (3 papers, 2021 to 2026). Bulging or ballooning in an area of an artery secondary to arterial wall weakening. "Systemic CXCL1 neutralization is a promising potential therapy to improve aneurysm healing by modulating the inflammatory response after coiling." (PMID 41743683, 2026). "CXCL1 expression was compared between aneurysms and sham-operated carotid arteries." (PMID 41743683, 2026).
brain injury (3 papers, 2013 to 2023). Acute and chronic (see also brain INJURIES, CHRONIC) injuries to the brain, including the cerebral hemispheres, CEREBELLUM, and brain STEM. "In this cell type HBO2 also had ameliorating effects on high levels of CXCL1 following LPS stimulation or traumatic brain injury, which resulted in alleviated inflammation and injury." (PMID 37946314, 2023). "Cortical neuron-derived exosomes containing miR-181c-3p have been shown to inhibit neuroinflammation in an ischemic brain injury rat model by downregulating chemokine (C-X-C motif) ligand 1 (CXCL1) in Astrocytes." (PMID 33178687, 2020). "CCL2, CXCL1 and CX3CL1 all stimulate the proliferation and migrationof vascular endothelial cells, which indicates that these chemokines have similar actions onneovascularization after brain injuries." (PMID 23627909, 2013).
brain tumor (3 papers, 2024 to 2025). "CXCL1 is involved in tumorigenesis in brain tumors, where it increases the proliferation of glioblastoma cancer cells." (PMID 38673949, 2024). "In other brain tumors, CXCL1 expression may be downregulated relative to healthy brain tissue, e.g., in diffuse astrocytomas, or not different relative to healthy brain tissue." (PMID 38673949, 2024).
colorectal adenoma (3 papers, 2011 to 2015). An adenoma that arises from the colon or rectum. "Our analyses showing CXCL1 overexpression in most colorectal adenomas and its low inverse correlation with TNM stages suggest that CXCL1 has important roles in both CRC initiation and tumor progression." (PMID 26104296, 2015). "CXCL1 expression is up-regulated in colorectal adenomas and adenocarcinoma, inhibiting apoptosis and inversely linked to expression of fibulin-1, an extra-cellular matrix protein implicated in control of tumour cell migration." (PMID 21249124, 2011). "The angiogenic and inflammatory function of CXCL1 in colorectal adenoma may contribute to new blood vessel formation and the recruitment of important supporting stromal and inflammatory cells that are critical to tumor initiation of tumor growth." (PMID 26104296, 2015). "Whereas normal human tissues uniformly showed low baseline CXCL1 and IL8 levels, these levels were greater than three standard deviations above normal in most human colorectal adenoma, adenocarcinoma and metastases to the liver and lung." (PMID 26104296, 2015). "In situ hybridization could confirm the upregulation of CXCL1 and downregulation of CA7 in colorectal adenomas and tumors compared to healthy controls." (PMID 26208990, 2015).
cutaneous melanoma (3 papers, 2015 to 2025). A primary melanoma arising from atypical melanocytes in the skin. "Importantly, we detected significantly elevated concentrations of the CXCR2 ligand CXCL1 in skin melanoma lysates as compared to plasma." (PMID 33578808, 2021). "Strikingly, mRNA expression levels for IL-6, G-CSF, CXCL1, and other known tumor-promoting inflammatory factors showed strong positive correlation with those of PTGS2 in samples from human cutaneous melanoma." (PMID 26343581, 2015).
delirium (3 papers, 2023 to 2025). A disorder characterized by confusion; inattentiveness; disorientation; illusions; hallucinations; agitation; and in some instances autonomic nervous system overactivity. "Overall, delirium was correlated with several cytokines (decreased IL-22, IL-21, IL-1α), chemokines (increased CXCL1, CCL11, CXCL13), and growth factors (increased HGF, and a tendency towards increased VEGF-A)." (PMID 41219650, 2025). "We identified several soluble factors and immune cell types linked to delirium, including IL-1α, IL-22, IL-21, CCL11, CXCL1, CXCL13, and VEGF-A, as well as exhausted B cells and activated T cells." (PMID 41219650, 2025). "IL-6, IL-8, IL-10, IL-18, TNF-α, and chemokines (CCL2, CCL3, CXCL1, and CXCL10) have also been reported to be elevated in ICU delirium patients and are associated with delirium severity." (PMID 39308447, 2024). "CXCL1, increased in the CSF of delirium cases, has been previously shown to be elevated in the CSF of people with neuroinflammation." (PMID 37759795, 2023). "Notably, CCL11, CXCL1, CXCL13, and VEGF-A remained significantly associated with delirium after adjusting for confounding factors." (PMID 41219650, 2025). "While CXCL1 has been previously associated with delirium, associations with CCL11, CXCL13, and VEGF-A are novel findings, likely due to limited prior investigations of these markers in delirium." (PMID 41219650, 2025).
dementia (3 papers, 2019 to 2025). Loss of intellectual abilities interfering with an individual's social and occupational functions. "TNF remained associated with higher risks of incident dementia in the ε4 stratum and CXCL1 was associated with higher risks of incident dementia in the ε3 stratum." (PMID 37584418, 2023). "Our study highlights the changes and potential contributions of several chemokines (CXCL1, CCL3, CXCL5, CXCL6, CCL3, CCL19), interleukins (IL8, IL6-RA, IL18-BP), and other immune markers (OSM, ALCAM, OPG, CHIT1, YKL-40, STAMBP, MMP-9, MMP-10) in the prodromal and dementia phases of AD." (PMID 31694701, 2019).
diabetic retinopathy (3 papers, 2024 to 2025). "Cxcl1 expression was recently shown to be a mediator of neutrophil recruitment and the pathogenesis of diabetic retinopathy, perhaps through pericyte-mediated alterations in retinal vessel barrier function, which may require IL-17a." (PMID 41002438, 2025). "Neutrophils respond to CXCL1 through activation of CXCR2, and this cytokine is elevated in the retinas of individuals with diabetic retinopathy." (PMID 39875729, 2025).
dry eye (3 papers, 2021 to 2024). "CXCL1 is an antimicrobial protein that is a chemoattractant for neutrophils, which have been implicated in dry eye." (PMID 34349764, 2021). "We have also found an increase in CXCL1 in the tears of aged mice that develop dry eye." (PMID 38560382, 2024).
enteritis (3 papers, 2020 to 2026). Inflammation of the small intestine. "We assessed the impact of Atg16l1-deficiency on PUFA-induced CXCL1 (C-X-C motif chemokine ligand 1) expression, as this chemokine (besides CXCL2) was potently induced in our model system and contributes to enteritis in Gpx4+/-IEC mice." (PMID 41382985, 2026). "PUFA-induced RXRα activity in Paneth cells governed chronic transmural enteritis by enabling the expression of CXCL1." (PMID 41365295, 2025).
eosinophilia (3 papers, 2015 to 2022). "However, including CXCL1 during allergic sensitization did reduce the eosinophilia seen after 6 daily OVA challenges." (PMID 35191395, 2022). "Our data suggest that ACh has distinct effects associated with fungal allergen-induced pulmonary inflammation, on the one hand, promoting ILC2 cytokine production and eosinophilia, and on the other hand, inhibiting neutrophilia via suppression of CXCL1 and CXCL2 expression." (PMID 35711456, 2022).
gestational diabetes mellitus (3 papers, 2022 to 2023). "CXCL1 levels are also elevated in the blood of patients with gestational diabetes mellitus and neonates whose mothers had gestational diabetes mellitus." (PMID 35806156, 2022). "However, the importance of CXCL1 in gestational diabetes mellitus remains to be investigated." (PMID 35806156, 2022). "In a human study, serum levels of angiogenic (CXCL1 and CXCL12) were higher in gestational diabetes mellitus mothers (GDMM)." (PMID 37928902, 2023). "In addition, CXCL1 levels are also elevated in patients with T2DM and gestational diabetes mellitus, leading to decreased insulin secretion and degraded islet function." (PMID 36675322, 2023).
Glucose intolerance (3 papers, 2017 to 2024). Glucose intolerance (GI) can be defined as dysglycemia that comprises both prediabetes and diabetes. "Treatments with either Cxcl1 or IL-1β restored the mature β cell phenotype and rescued MyD88-deficient mice from glucose intolerance, indicating the Cxcl1/IL-1β axis as a potential therapeutic target." (PMID 38885342, 2024). "Next, we tested the contribution of Cxcl1 loss to glucose intolerance in ΔMyD88Peri mice." (PMID 38885342, 2024). "Thus, the low levels of pericytic Cxcl1 in ΔMyD88Peri mice likely contributed to their β cell failure and glucose intolerance." (PMID 38885342, 2024).
hearing loss (3 papers, 2022 to 2025). "Our findings support this proposed mechanism, as RGS17 depletion blocks CXCL1 production in hair cells and protects against cisplatin-induced hearing loss." (PMID 40061942, 2025). "Trans-tympanic administration of SB225002, a chemical inhibitor of CXCR2 (receptor target for CXCL1) reduced immune cell migration, protected against cisplatin-induced hearing loss and preserved hair cell integrity." (PMID 37063917, 2023).
Hydrocephalus (3 papers, 2021 to 2025). Hydrocephalus is an active distension of the ventricular system of the brain resulting from inadequate passage of CSF from its point of production within the cerebral ventricles to its point of absorption into the systemic circulation. "Cxcl1/KC (keratinocyte-derived chemokine) as the intermediating cytokine of hydrocephalus in ApoE-knockout/APOL1-G1 mice." (PMID 39803526, 2024). "CXCL1 is elevated in brain tissue from hydrocephalic mice with genetically induced ciliary dysfunction, in which hydrocephalus develops concurrent with neuroinflammation and tissue injury." (PMID 34863228, 2021). "Elevated CXCL1 in iNPH patients may therefore reflect presence of neuroinflammation and it may arise concomitantly with development of hydrocephalus." (PMID 34863228, 2021).
hyperlipidemia (3 papers, 2014 to 2023). "In accordance, both CCL7 and its receptor CCR2, as well as CXCL1 have been implicated in monocyte mobilization from the bone marrow in steady state and under conditions of hyperlipidemia, respectively." (PMID 31641089, 2019). "Interestingly, endothelial CXCL1 has recently been shown to play a crucial role in hyperlipidemia-induced arterial leukocyte arrest." (PMID 24879339, 2014).